PHOSPHO2 (phosphatase, orphan 2)
Description:
Phosphatase that has high activity toward pyridoxal 5'-phosphate (PLP). Also active at much lower level toward pyrophosphate, phosphoethanolamine (PEA), phosphocholine (PCho), phospho-l-tyrosine, fructose-6-phosphate, p-nitrophenyl phosphate, and h-glycerophosphate.
Synonyms: MGC22679
Tractability: No criterion of Open Targets' tractability assessment is met for any kind of drug.
Gene: Protein-coding gene on chromosome 2 (169,694,440 to 169,704,808, forward strand). Ensembl gene ENSG00000144362.
Subcellular location (Human Protein Atlas): Vesicles; Nucleoplasm
Gene Ontology:
Molecular function: protein binding; pyridoxal phosphatase activity; phosphatase activity
Genetic constraint (gnomAD): Loss-of-function variants: 14 observed, 16.85 expected, observed/expected ratio (o/e) 0.83, 90% interval 0.55 to 1.3. The upper end of that interval is the gene's LOEUF score, 1.3, which puts it in group 5 of 6, group 1 being the genes least tolerant of losing a copy. Missense variants: 244 observed, 292.27 expected, observed/expected ratio (o/e) 0.83, 90% interval 0.75 to 0.93. Synonymous variants: 84 observed, 94.07 expected, observed/expected ratio (o/e) 0.89, 90% interval 0.75 to 1.07.
Homologues: Orthologues: chimpanzee PHOSPHO2 (99% identical), macaque PHOSPHO2 (98% identical), dog PHOSPHO2 (88% identical), pig PHOSPHO2 (87% identical), guinea pig PHOSPHO2 (86% identical), mouse Phospho2 (80% identical), rat Phospho2 (79% identical), tropical clawed frog phospho2 (61% identical), zebrafish phospho2 (48% identical), Drosophila melanogaster CG12237 (36% identical), Drosophila melanogaster CG14212 (29% identical). Paralogues in human: PHOSPHO1 (41% identical).
Diseases named in the same sentence as PHOSPHO2 in open-access papers:
PHOSPHO2 is named in the same sentence as 4 diseases in open-access papers, as found by Europe PMC text mining. Sharing a sentence is not in itself a finding about the gene and the disease. The quoted sentences say what the papers report.
tumor (2 papers, 2022 to 2025). "The result of model with 10 genes showed that 6 genes of MYCN, NDRG1, TXNRD1, SNAPC2, PHOSPHO2 and CDCA8 were more significantly associated with diagnosis of tumor according to the statistical filter of P < 0.05." (PMID 40465781, 2025). "Among these genes, PHOSPHO2, KLHL23, TRIM39, TSNAX-DISC1 and RPP21 expression were significantly elevated in the tumor tissues compared with the non-tumor tissues of HCC according to TCGA database." (PMID 35833210, 2022). "This study found that several genes including PHOSPHO2, KLHL23, TSNAX-DISC1, TRIM39 and RPP21 were upregulated by SOF and the expression levels of these genes were higher in tumor than in non-tumor parts of patients with HCC according to the TCGA database." (PMID 35833210, 2022).
PHOSPHO2 also shares sentences with these, for which no sentence is quoted: cancer (1 paper); epilepsy (1); liver cancer (1).